ETV4 (ETS variant transcription factor 4)
Diseases named in the same sentence as ETV4 in open-access papers (continued):
Sharing a sentence is not in itself a finding about the gene and the disease.
tumor (continued). "Studies have shown that ETV4 is abnormally expressed in a variety of tumors, and promotes tumor progression through stimulating tumor cell proliferation and metastasis." (PMID 36059531, 2022). "ETS variant 4 (ETV4), a well-known member of the PEA3 subfamily of ETS-domain transcription factors, has also been reported to be involved in tumor metastasis in multiple types of cancers." (PMID 33407520, 2021). "Although the complex factors and signaling pathways involving EMT and angiogenesis remain poorly understood, however, we give some new insight into the specific molecular mechanisms mediating the anti-tumor effect of miR-29b-targeted inhibition of ETV4 in CRC." (PMID 33407520, 2021). "To probe the effect of ETV4 on tumor growth in vivo, we first established stable ETV4 knockdown MDA-MB-231 cells using lentiviral vectors." (PMID 34052833, 2021). "In spite of an increasing understanding of the role of ETV4 in tumor progression, the current study, to our knowledge, provides the first evidence for involvement of ETV4 in cancer metabolism reprogramming." (PMID 34052833, 2021). "The results showed that miR-29b and ETV4 expressions were unrelated to age, gender, tumor size, and tumor location." (PMID 33407520, 2021). "These CAM tumors as well as the CD-292 CAM tumor were collected and lysed, and the presence of ETV4 was examined by carrying out Western blot analysis using antibody against human ETV4 protein." (PMID 34685592, 2021). "ETV4 and FABP6 were co-expressed in tumor samples and significantly associated with metastasis in CRC." (PMID 33648461, 2021). "To verify that ETV4 has a tumor promoting activity in the CRC cells, we generated ETV4-overexpressing and ETV4-knockdown CRC cell lines." (PMID 32042269, 2020). "Levels of ETV4 expression in the xenografted tumor masses of mice bearing KKU-213 and KKU-139 were also significantly increased in the E2 group and diminished in cells from mice treated with TAM." (PMID 29467595, 2018). "Immunocytochemistry performed on paraffin-embedded mouse tumor tissue sections showed an equivalent Ki-67 expression in tumors from ETV4 + shCtrl and ETV4 + shMMP13 cells, which all show proliferative activity." (PMID 29996935, 2018). "ETV4 inhibition decreasing tumor cell invasion is consistent with ETV4 overexpression promoting invasion and metastatic potential via increased MMP expression and epithelial-to-mesenchymal transition (EMT) in other tumors." (PMID 29371979, 2017). "Other data have shown that expression and activation of ETV4 is correlated with activation of PI3K signaling in tumor progression, and ETV4 knockdown resulted in a downregulation of phospho-AKT." (PMID 29371979, 2017). "ETV4 mRNA expression correlated with tumor mitotic rate in primary and metastatic GIST (left and middle)." (PMID 29371979, 2017). "In fact, there was a greater than 6-fold reduction in tumor size in ETV4 silenced S2 cells compared to control cells, which is substantial for the S2 GIST cell line." (PMID 29371979, 2017). "The present study suggests that Etv4 and Etv5 play an important role in tumor progression by altering chromatin accessibility and gene expression during EMT." (PMID 28446749, 2017). "ETV4 also promoted tumor malignancy by stabilizing nuclear β-catenin, and synergizing with the PI3K/Akt pathway to drive activation of Wnt/β-catenin." (PMID 29371979, 2017). "In mouse flank tumor xenografts, ETV4 silencing also inhibited GIST882 tumor growth, as well as tumor proliferation by Ki-67 staining." (PMID 29371979, 2017). "We show that the inhibition of ACLY, ACC1 or ETV4 paradoxically allows tumor cells to survive better under hypoxia." (PMID 26452058, 2015). "Significantly, c-kit strongly promoted tumor cell invasiveness by increasing ETV4, which induced MMP7 expression and epithelial-mesenchymal transition (EMT) via ERK pathway." (PMID 26356816, 2015).
tumor (continued). "In situ hybridization was carried out for the ets variant ETV4 (PEA3) (23 cases) as well as MMP-9 (19 cases) and MMP-14 (13 cases), demonstrating high mRNA expression in the tumor cells." (PMID 16042759, 2005). "This bidirectional regulation of FGL1 by ETV4 suggests a complex relationship between these two proteins, which may vary depending on the tumor type and cellular context." (PMID 40469297, 2025). "In immunocompetent murine models, ETV4 downregulation significantly suppressed tumor growth." (PMID 41502516, 2025). "In most tumors, ETV4 exhibited a negative association with the majority of tumor-infiltrating lymphocytes (TILs)." (PMID 40469297, 2025). "Furthermore, our scRNA-seq analysis revealed that ETV4 was detected in cancer-associated fibroblasts (CAFs), a finding that points to the potential function of ETV4 in stromal remodeling and stromal-immune-tumor interactions." (PMID 41502516, 2025). "By immunohistochemistry, tumor cells also expressed vimentin, and ETV4." (PMID 39442927, 2025). "This suggests that Etv4 downregulation benefits the immune system’s anti-tumor response." (PMID 41502516, 2025). "The impact of ETV4 on tumor growth and distant metastasis was then investigated in vivo." (PMID 41281746, 2025). "In contrast, ETV4 knockdown reduced HCT116 cell-derived xenograft tumor growth." (PMID 41281746, 2025). "Additionally, ESM1 and ETV4 are enriched in inflammatory and viral carcinogenesis pathways and play significant roles in remodeling the tumor microenvironment." (PMID 40722723, 2025). "Restoring CIC repressor activity or silencing of its target genes Etv4 and Etv5 decreases resistance to MAPK pathway inhibition, similar to treatment with drugs (PFK15 and Tx-1123) that selectively affect the viability of Cic-deficient tumor cells." (PMID 41219537, 2025). "Additionally, ETV4 regulates the expression of cytokines and cytokine receptors such as CCL2 and CXCR4, promoting tumor-associated macrophages (TAMs) and MDSCs recruitment and fostering an immunosuppressive microenvironment." (PMID 41502516, 2025). "ETV4 shows differential expression across various cancer types and may serve as a potential prognostic biomarker in certain tumor types." (PMID 40469297, 2025). "For example, targeting metabolic enzymes or cytokine signaling pathways regulated by ETV4 could serve as alternative routes to reprogram the tumor immune microenvironment." (PMID 41502516, 2025). "Notably, ETV4 was recently correlated with poor survival, as well as with immune cell infiltration, tumor heterogeneity and stemness in a pan-cancer cohort in TCGA." (PMID 39494610, 2024). "Furthermore, our pathology results showed that ETV4 expression levels positively correlated with infiltrated MPO+ or CD66b+ TANs levels in the tumor tissues." (PMID 36670069, 2023). "ETV4 expression was compared to stemness indices across various tumor types." (PMID 37205199, 2023). "Noticeably, knockdown of ETV4 significantly decreased lymphangiogenesis in footpad tumor." (PMID 36670069, 2023). "Together these results indicate that ETV4 may accelerate tumor genesis and prognosis by regulating tumor heterogeneity." (PMID 37205199, 2023). "Together, these results might indicate that ETV4 promoted LN metastasis depending on both TANs‐mediated lymphangiogenesis and tumor‐intrinsic migration and invasion." (PMID 36670069, 2023). "The current study confirmed that ETV4 expression was positively correlated with indices of tumor stemness in most tumor types, suggesting that elevated ETV4 expression may enhance tumor proliferation, metastasis, therapy resistance, and recurrence in general." (PMID 37205199, 2023). "To examine whether this effect of ETV4 on tumor heterogeneity is a common phenomenon, we calculated the association between ETV4 and TMB, tumor purity, MSI, NEO, HRD, MATH, LOH, and tumor ploidy among multiple types of cancers." (PMID 37205199, 2023).
tumor (continued). "Similarly, the analysis of Lee Bladder Cohort from the Oncomine database also indicated that ETV4 was upregulated in tumor tissues compared to normal adjacent tissues." (PMID 36670069, 2023). "Since the secretion of CXCL1 and CXCL8 by cancer cells promoted TANs recruitment to the tumor sites, we hypothesized that ETV4 might promote TANs accumulation." (PMID 36670069, 2023). "In CRC, the expression of ETV4 mRNA is significantly high, and it is significantly positively correlated with the depth of invasion, lymph node metastasis, and tumor progression, suggesting that ETV4 can be used as a prognostic marker for CRC progression and metastasis." (PMID 34736492, 2021). "The signals that induce the expression of ETV4 in MSS tumour cells are not yet fully understood." (PMID 34824625, 2021). "Molecular characterization of the CAM tumor employing markers such as cyclin D2, ETV4 or WT1 could thus be carried out." (PMID 34685592, 2021). "Immunohistology of the CAM tumor using an antibody against ETV4 exhibited staining of ETV4." (PMID 34685592, 2021). "ETV4 is a TF that is known to be involved in tumor development and progression." (PMID 34623791, 2021). "Therefore, we evidentially show that ETV4 promotes tumor progression by transcriptionally regulating MMP1 in PTC cells." (PMID 32982961, 2020). "Thus, MMP13 acts as a relay of ETV4 in its functional role in the mammary epithelial tumorigenic cells in vitro as well as in tumor development in animal models." (PMID 29996935, 2018). "The role of ETV4 on cell proliferation was also investigated using 3D tumor spheroid-based assay." (PMID 29467595, 2018). "ETV4 is now well known to be involved in events participating in tumor development and progression." (PMID 29996935, 2018). "ETV4 downregulation in MMT cells leads to a decrease in their tumor-forming abilities." (PMID 29996935, 2018). "Furthermore, we demonstrated that MMP13 inhibition disturbs proliferation, migration, and invasion induced by ETV4 and participates to ETV4-induced tumor formation in immunodeficient mice." (PMID 29996935, 2018). "Moreover, ETV4 knockdown inhibited the Wnt/β-catenin signaling pathway, which we recently identified to contribute to tumor malignancy in GIST." (PMID 29371979, 2017). "ETV4 knockdown in GIST882 cells reduced tumor cell viability and invasion in vitro." (PMID 29371979, 2017). "Taken together, ETV4 regulated tumor cell growth both in vitro and in vivo." (PMID 29371979, 2017). "ETV4 knockdown also reduced tumor cell proliferation, invasion, and tumor growth in vivo." (PMID 29371979, 2017). "Interestingly, they include EGR1, ETV4, ETV5 and FosB that have been associated with EMT and tumour aggressiveness in several cancers." (PMID 28651004, 2017). "Knockdown of ETV4 suppressed cell proliferation, tumor invasion, and growth." (PMID 29371979, 2017). "Meanwhile, ETV4 mRNA expression was variable and correlated with tumor aggressiveness." (PMID 29371979, 2017). "Recent studies have shown that ETV4 could enhance tumor cell invasiveness by increasing MMPs and inducing EMT." (PMID 26356816, 2015). "Importantly, this showed that the regulation between ACC1/ACLY and ETV4 was relevant in tumor expression datasets." (PMID 26452058, 2015). "Collectively, these data suggest that c-kit could enhance tumor cell invasion by promoting ETV4 expression through activating MEK/ERK pathway." (PMID 26356816, 2015). "MDA-PCa-2b and PC3 cells were thus used as suitable models to investigate whether ETV1 and ETV4 have similar mechanistic and functional involvement in tumor biology." (PMID 25595908, 2015). "In the light of previous studies, we hypothesized that c-kit signaling could increase ETV4 expression and promote tumor cell invasiveness in CRMAC." (PMID 26356816, 2015).
tumor (continued). "Although no clear correlations between the expression level and patient outcome were observed here, the genes TOP2A, ETV4 and BIRC5 are interesting candidate targets for the 17q gain associated with poor outcome, but further validation is required on a larger tumor set." (PMID 18522746, 2008). "Targeting ETV4 may be an effective strategy to inhibit tumour metastasis." (PMID 39163517, 2024). "However, a 3–4-day measurement of tumor size over the course of 10 more days (until animals were killed) indicated that MMP13 expression was required for optimal tumor growth because MMP13-shRNA-expressing ETV4 cells are, on average, twofold smaller than controls." (PMID 29996935, 2018). "Furthermore, in many studies, the roles of ETV4 in various types of tumor have been reported." (PMID 29467595, 2018). "Thus, high levels of ETV4 expression contributed to tumor malignancy, as did β-catenin." (PMID 29371979, 2017). "In addition, overexpression of Pea3/ETV4 was shown to result in increased levels of vimentin, the intercellular adhesion molecule ICAM-1, osteopontin, vascular endothelial growth factor and cyclooxygenase-2, thus providing evidence for the importance of PEA3/ETV4 in tumor formation and metastasis." (PMID 28158215, 2017). "Considering the absence of an overlap between ETV1 target genes in vitro and in vivo, we questioned whether we could use the observed impact of ETV1 and ETV4 silencing in invasion and AIG to find phenotype-associated genes that could be useful as markers of tumor aggressiveness in vivo." (PMID 25595908, 2015). "ETV1, ETV4, and ETV5 can enhance the proliferation, migration, and invasion of tumor cells, thereby leading to tumor progression, metastasis, and drug resistance." (PMID 39668941, 2025). "Together, these results indicate that ETV4 and ETV5 are involved in tumor cell proliferation and are the main mediators of drug resistance upon inactivation of CIC." (PMID 41219537, 2025). "The results indicated that CDC73, PSMC2, SOCS3, and ETV4 were substantially upregulated in tumor group than that in control group, whereas PLK2 and LMO7 were substantially downregulated in tumor group than that in control group." (PMID 41318472, 2025). "We compared the expression levels of ETV1, ETV4 and ETV5 mRNA between the non‐tumour brain samples and GBM samples from the TCGA and Rembrandt databases." (PMID 40275610, 2025). "In summary, before the absence of molecular and methylation profile confirmation, the microscopic morphology combined with WT1, ETV4, NUT and other immunohistochemical staining is helpful for the diagnosis and differential diagnosis of this tumor." (PMID 40255429, 2025). "Violin plots demonstrated significantly elevated activities of IRF5, IRF8, KLF2, TFAP2B, and MAFK in Zbp1−/− tumor cells, while E2F4 and ETV4 were preferentially activated in WT tumors." (PMID 41430036, 2025). "ETV4 and ETV5 of the ETS family are involved in cancer stemness and metabolic reprogramming, whereas TNFRSF14 inhibits tumor growth through apoptotic signaling." (PMID 41304759, 2025). "Therapeutically, the KC1 tumours exhibit significant sensitivity to MEK inhibitors, likely due to the elevated expression of DUSP4/6 and ETV4, key regulators of the MAPK signalling pathway." (PMID 41025426, 2025). "In vivo experiments corroborated that the downregulation of ETV4 leads to reduced expression of SLC7A11, thereby inhibiting tumor development." (PMID 39917169, 2025). "Conversely, WT tumor cells showed leading proliferation-promoting TFs (E2F4 and ETV4), aligning with rapid cell cycle advancement and glycolytic reprogramming." (PMID 41430036, 2025). "Knockdown of ETV4, meanwhile, inhibited PTC progression by down‐regulating the expression of SLC7A11, which promoted the tumour ferroptosis effect." (PMID 39163517, 2024).
tumor (continued). "Specifically, epigenetic mechanisms represented by m6A, NcRNA and some key regulatory proteins, such as GPX4, CD71, ETV4 and SIRT6, interfere with TC progression by regulating tumour cell ferroptosis." (PMID 39163517, 2024). "Pharmacological inhibition of FGFR signaling also suppressed tumorigenesis, prevented MAPK signaling and downregulated the expression of the ETV4 and ETV5 transcription factors, which were overexpressed in human and mouse tumor samples." (PMID 38916046, 2024). "We next examined the degree of MAPK pathway inhibition after treatment in tumor cells using an MAPK gene expression signature score based on changes in the MAPK-regulated transcripts (DUSP6, ETV4, ETV5 and SPRY4) in tumor epithelial cells." (PMID 36702949, 2023). "By analyzing RNA‐sequencing date from TCGA database, we identified that only ETV4, a potential CXCL8 regulator, was highly expressed in tumor tissues compared to normal adjacent tissues (NATs)." (PMID 36670069, 2023). "We found that among all ETS family transcription factors, ETV4 and ETV5 consistently demonstrated the highest Pearson correlation coefficient between each other in both the cell line and primary tumor datasets." (PMID 36509998, 2023). "We demonstrated that the tumor suppressive is mediated by both positively and negatively acting downstream effectors, including CBX6, TRIB3, ETV4 and FOS/JUN, where the first two also affect the differentiation status of Lp30 AML." (PMID 36631623, 2023). "Other genes, such as ETV4, ETV5, CCND1, EPHA2, and EPHA4, also play a role in activating the MAPK pathway, promoting tumor resistance to MEKi." (PMID 36437939, 2022). "ETV1, ETV4, and ETV5 comprise the PEA3 transcription factor subfamily and were found to be significantly related to numerous tumor markers." (PMID 35860243, 2022). "Collectively, our results demonstrate the tumor-suppressive effects of quercetin in RMS and present a hitherto undescribed mechanism of PANX1 regulation via ETV4-mediated transcription of a translationally functional 5′ leader-containing PANX1 mRNA." (PMID 35194046, 2022). "We explored the correlation of ETV1, ETV4, and ETV5 with tumor-infiltrating immune cells (TIICs) in CRC tumor microenvironments via the Tumor Immune Estimation Resource (TIMER) and Gene Expression Profiling Interactive Analysis (GEPIA)." (PMID 35860243, 2022). "It is interesting to note that, ETV4, RNF43 and AXIN2 are highly correlated with tumour cell purity." (PMID 34824625, 2021). "A xenograft assay validates the tumor growth-impeding effect and inhibition of CXCR4/SHH/GLI1 signaling cascade after ETV4 depletion." (PMID 34052833, 2021). "ETV4 stimulates tumor metastasis, while CCNE controls tumor survival through the CCNE–CDK2 cell cycle complex." (PMID 34685592, 2021). "Our findings demonstrate that CIC functions as a tumor suppressor in CRC cells and highlight ETV4, among the PEA3 group transcription factors, as a strong promoter of cancer progression and as a critical target of CIC in the context of CRC." (PMID 32042269, 2020). "Our results additionally showed that ETV4 induces tumor growth, cell migration, and the EMT process by interfering ETV4 expression in PTC cells." (PMID 32982961, 2020). "We demonstrated that CRLF1 interacts with MYH9, promoting tumor proliferation and metastasis by activating ERK/ETV4; therefore, we provide a prospective therapeutic target for the treatment of PTC." (PMID 32982961, 2020). "For instance, overexpression of ETV4, ELF3, and ETV5 facilitates tumor angiogenesis, growth, invasion and metastasis, and indicates poor prognosis." (PMID 33585247, 2020). "The prognostic significance of the lymph node status (P = 0.000016), macroscopic tumor size (P = 0.0028), and combined MMP13 and ETV4 mRNA level was maintained." (PMID 29996935, 2018). "A correlation of ETV4 with HER2/Neu overexpression, tumor grade, and recurrence in human breast cancer patients has also been reported." (PMID 30460327, 2018).